MYC (MYC proto-oncogene, bHLH transcription factor)
Diseases named in the same sentence as MYC in open-access papers (continued):
Sharing a sentence is not in itself a finding about the gene and the disease.
tumor (continued). "We evaluated expression changes of several key epigenetic-regulated tumor-related genes including p16INK4a (p16), p21WAF1 (p21), BMI1 and c-MYC." (PMID 23342141, 2013). "The pathway analysis indicated alterations in PI3K/Akt, MYC and NF-κB signaling pathways, and potential critical roles for TGFA, ErbB2, and IL-1/IL-1R which may promote angiogenesis, tumor growth, and metastasis and hence cause the aggressive phenotype observed in young women." (PMID 23704896, 2013). "A high-level CCND3 tumor (Case OC-07) showed co-amplification of MYC and AKT2; and a high-level MYC tumor (OC-08) was co-amplified for JAK2, FGFR3, and MYB." (PMID 23289505, 2013). "MRNA levels of two tumor suppressor genes, p16 and p21, were significantly increased (p<0.01), whereas the expression of two tumor promoting genes, BMI1 and c-MYC, were dramatically decreased (p<0.01) in response to GE treatment." (PMID 23342141, 2013). "The status of ERK, JNK, c-MYC and c-JUN were also compared in xenograft tumor tissues by immunohistochemical staining." (PMID 23650533, 2013). "We also did not observe any positive correlation between LIN28A and LIN28B and MYC at the mRNA level in TCGA dataset or by IHC between LIN28A and MYC on our 80 GBM tumor tissue microarray." (PMID 23846349, 2013). "Co-treatment of VPA and temsirolimus synergistically inhibited the tumor cell growth and triggered the autophagic cell death, with a significant inhibition of MTOR signaling and MYC oncoprotein." (PMID 23866964, 2013). "Among the genes down-regulated in our data set was MYC, which was previously shown to be silenced by BET inhibitors in a number of tumor types." (PMID 24293458, 2013). "The tumor suppressive roles of let-7 are further strengthened by its antagonistic roles toward the expression of multiple oncogenes including RAS, MYC, and other cell cycle regulators in a variety of human cancer tissues." (PMID 23075324, 2012). "Given that let-7 simultaneously inhibits multiple oncogenic pathways that are involved in most steps of tumorigenesis (such as RAS, MYC, and HMGA2), restoration of let-7 expression in tumor cells provides a novel therapeutic strategy to treat cancer." (PMID 22970210, 2012). "The lack of potent Ras and c-Myc inhibitors and the acquirement of drug resistance make ERK3, ERK4, and MK5 attractive targets for therapeutic drugs in tumours with perturbed RAS, RAF or c-MYC activity." (PMID 22800433, 2012). "Further, overexpression of BCL-2 or BCL-XL in these mice or in transplanted bone marrow cells accelerates MYC-driven tumor development, suggesting that BCL-2 and BCL-XL act in synergy with MYC in tumorigenesis." (PMID 22393362, 2012). "The C3TFT gene-sets that were more highlyexpressed in the tumour tissue had common regulatory motives for various E2Fs, NRF2, ARNT, NRF1, MYC and YY1." (PMID 23009663, 2012). "In the c-Myc tumor model, significant c-MYC expression is predominantly contributed by the LAP-tTa-Tet-O-MYC system." (PMID 23024800, 2012). "For example, MYC, the most frequently amplified gene in our patient samples, was determined to be significantly overexpressed in macrodissected samples, but not in those that were microdissected, although this result may be due to relatively small sample size or heterogeneity within the tumor." (PMID 21635755, 2011). "In some types of tumour cells, CIP2A depletion leads to impaired proliferation potential largely due to diminished MYC expression." (PMID 22075943, 2011). "From the results of the microarray analysis, we selected 5 genes i.e., K-ras, c-MYC, DNMT1, Tpd52, CDKN1b for PCR confirmation because they are already considered as tumor-related genes." (PMID 22206623, 2011).
tumor (continued). "All the tumor biopsies of animals inoculated with ACP03 (CL, CLCA1 and CLCA2 groups) presented MYC protein overexpression." (PMID 21811552, 2011). "In accord with their tumor-suppressive role, members of the let-7 family target cell cycle regulators and oncogenes like RAS, HMGA1/2, MYC, IGF2BP1 and LIN28." (PMID 21835047, 2011). "Let-7a target genes relevant to transformation and subsequent tumor development include RAS, MYC, IGF2BP1 and HMGA2." (PMID 21853155, 2011). "As expected from the SNP-array data, the MYC and BIRC7 relative transcript levels were up-regulated in 15/18 (83%) and 14/18 (78%) tumours analyzed, respectively." (PMID 21060790, 2010). "Proto-oncogenessuch as MYC and RAS promote normal cell growth but fuel tumor developmentwhen deregulated." (PMID 20445224, 2010). "Our data are consistent with a regulatory feedback loop between c-MYC and IRP2 that controls tumor growth." (PMID 20405006, 2010). "Whereas c-MYC expression was uniform in all pleomorphic clusters, C-RAF and c-MYC transgene expression in columnar tumor foci was heterogeneous and decreased at late stages suggesting fluctuation of gene expression." (PMID 19551151, 2009). "First, the tumor incidence at two weeks and two months of age is the same for SpC-C-RAF BxB single and SpC-C-RAF BxB/SpC-c-MYC compound mice." (PMID 19551151, 2009). "BCL2, MYC, CCND2, BCL6 and LMO2 expression was studied in tumor tissue from 12 DLBCL patients of our series using real-time PCR." (PMID 20016842, 2009). "Tumor bearing CMR mice on the whole exhibited tumor regression intermediate to that of the CR and CM mice following dual oncogene-inactivation of MYC and K-rasG12D oncogenes (n = 10)." (PMID 18461184, 2008). "Tumours in EμMYC/BCRHEL/sHEL and MMTV-rtTA/TRE-MYC/BCRHEL/sHEL mice responded to all immunosuppressive drugs tested as well as to cyclophosphamide." (PMID 18578571, 2008). "We suggest that the transcription factors SMAD3/4, GNB2L1/RACK1, MYC, MAX and JUN, whose functions have been extensively studied in tumours but only marginally in muscle, appear instead to play important roles in regulating muscle response to atrophy." (PMID 19108710, 2008). "Paradoxically, increased expression of putative c-MYC antagonists MAD1 and MXI1 was observed in tumour specimens." (PMID 18493233, 2008). "The tumors that arose in the Eμ-MYC/BCRHEL/sHEL and MMTV-rtTA/TRE-MYC/BCRHEL/sHEL mice expressed a neo-autoantigen (sHEL), which provided an autoimmune stimulus to the tumor cells." (PMID 18578569, 2008). "MYC, BARK1, and FASN protein expression were statistically significant predictors of Gleason score (P<0.001, P=0.023, P=0.036), representing tumour differentiation." (PMID 17146477, 2007). "Genes of this pathway up-regulated in CC tumor cells were JUN, MYC, FZD2, RAC1, GSK3B and CTNNB1, and a few others." (PMID 17822553, 2007). "Univariate analyses revealed a significant difference between tumour and benign hyperplastic tissue for immunohistochemical staining results of FASN (P<0.001), MYC (P<0.001), and PP1α (P=0.020), indicating a role of these proteins in tumour initiation." (PMID 17146477, 2007). "Six candidates, from whom antibodies for IHC analyses are available, were analysed in detail in a large tumour collection using tissue microarray technology: FASN, BARK1, PP1α, PP2A, NM23-H1, and MYC." (PMID 17146477, 2007). "Univariate correlations of protein expression with Gleason score and pT-stage were found for MYC, BARK1 and PP1α, indicating a role of these proteins in tumour progression." (PMID 17146477, 2007). "We conclude that HMECs transduced with ERα, BMI1, MYC and TERT readily form oestrogen-dependent tumours in mice." (PMID 17573968, 2007). "Furthermore, the impacts of circACTN4 on the MYC expression, CCNE1, and CDK4 were detected via immunohistochemistry (IHC) in transplanted tumor tissues." (PMID 40612865, 2025).
tumor (continued). "Interestingly, compared to normal tissues, SPP1+ TAMs-CAFs regulated tumor cells through the regulation of genes related to HCC tumorigenesis, including CCND1, MYC, CTNNB1, and BAX." (PMID 40230843, 2025). "In addition, BRD4 inhibitors, such as JQ1, have demonstrated success in targeting MYC-regulated super-enhancer networks in RMS, thereby disrupting transcriptional drivers of tumor proliferation." (PMID 40821216, 2025). "Furthermore, MLX also plays a pivotal role in MYC-induced tumorigenesis, underscoring the importance of MLX function in tumor development." (PMID 40073115, 2025). "MYC activates LAT1 and LAT3 expression and promotes effective EAAs uptake into tumor cells." (PMID 41008653, 2025). "However, overexpression of MYC with a GFI1 P2A mutant, which disrupts the latter’s SNAG domain, in neural progenitors prevented tumor formation in mice." (PMID 40479062, 2025). "Moreover, the recently identified MYCMI-6 and MYCMI-7 compounds, were shown to inhibit MYC/MAX hetero-dimerization and induce c-MYC and N-MYC protein degradation, exhibiting anticancer activity in in vivo tumor models." (PMID 40000737, 2025). "Moreover, MYC upregulates LAT1 and LAT3 expression and transcription, sustaining EAA metabolism in tumor cells." (PMID 41008653, 2025). "In our case for a negative control, we collected a tumour tissue from the MYC-induced liver tumour model without the administration of [U-13C] glucose and [amide-15N]." (PMID 39880930, 2025). "Western blot analysis of tumor tissues showed no significant changes in c-MYC protein levels but revealed reduced PTBP1 protein and c-MYC S62 phosphorylation levels, along with increased levels of Atg10, Beclin-1, P62, and LC3B." (PMID 40469179, 2025). "To confirm that the MYC-mRNA drug achieved on-target inhibition of c-MYC in the primary tumor to achieve therapeutic efficacy, we performed H&E staining of the tumors from the vector + nanocage, the 3× IC50, 6× IC50, and 9× IC50-treated tumor-bearing mice." (PMID 40949131, 2025). "For instance, in lung cancer, the co-activation of KRAS and c-MYC drives the recruitment of anti-inflammatory macrophages via CCL9 and IL-23, while simultaneously excluding T cells, B cells, and natural killer (NK) cells from the tumor site." (PMID 40333779, 2025). "Importantly, MYC is critically dependent on PVT1 levels: inhibition of PVT1 results in reduced MYC protein levels and impaired tumor growth, indicating that PVT1 plays a critical role in MYC-driven tumorigenesis." (PMID 40027648, 2025). "In an in vivo model, knockdown of FOSL2 in MYC‐overexpressing mouse LLC cells prior to establishing the C57BL/6J xenograft model did not alter subcutaneous tumor growth rate but greatly reduced CTC numbers and dissemination index." (PMID 39899538, 2025). "This study also suggests that c-MYC is not the only reprogramming factor responsible for tumor development, as iPSC-derived tumors have been reported even in the absence of c-MYC." (PMID 40541178, 2025). "APC regulates cell growth, and prevents tumor formation by modulating the Wnt signaling pathway, whose activation leads to the transcription of genes involved in tumorigenesis such as cyclin D1 (CCND1) and c-MYC." (PMID 40943367, 2025). "Similarly, targeting the interface between MYC and MIZ1 to disrupt the complex that contributes to the downregulation of certain pro‐immunogenic genes is likely to increase immune visibility of tumor cells in vivo." (PMID 40488968, 2025). "Moreover, TCGA-STAD data indicated that both MYC and TOP2A were markedly upregulated in tumor tissues compared to adjacent normal tissues." (PMID 40290723, 2025).
tumor (continued). "As a MYC antagonist, MNT was expected to be a tumor suppressor." (PMID 41140443, 2025). "MYC, a key regulator of oncogenic metabolism, promotes glycolysis (via LDHA, PFK1), glutamine metabolism (via GLS1), and mitochondrial biogenesis to fuel rapid tumor proliferation." (PMID 40814172, 2025). "The tumor suppressor FBXW7, which is frequently downregulated in adenocarcinomas, is not expressed in SCCPs, and this phenotype leads to the accumulation of oncoproteins (e.g., c-MYC) that drive invasiveness." (PMID 40746833, 2025). "Notably, these genes contained major BL-specific driver genes, such as CD9, MYC, TP63, and cJUN, indicating a direct tumor cell-intrinsic repression of BL features." (PMID 39762215, 2025). "Currently, it has been shown that there is a complex interaction between MYC and UPR signaling, and activation of both may jointly promote tumor progression." (PMID 40519919, 2025). "Silencing of PRMT5 leads to reduced MYCN levels and impaired tumor cell growth, suggesting that PRMT5 inhibitors could serve as potential therapeutic agents for MYC/MYCN-driven MB." (PMID 40365336, 2025). "In breast cancer, MYC amplification is observed in approximately 15%–30% of cases, particularly in triple-negative breast cancer (TNBC) and HER2-positive subtypes, where it drives aggressive tumor behavior and resistance to standard therapies." (PMID 40365020, 2025). "They reveal that MYC regulates YBX1 expression in both normal progenitors and tumor cells and identify a novel MYC-YBX1-PRC2 axis that may contribute to tumorigenesis." (PMID 40471378, 2025). "In pancreatic cancer, the low-sugar and hypoxia microenvironment promotes tumor progression by activating HIF1 α and c-MYC signals, and β-TrCP may indirectly regulate these pathways." (PMID 40534867, 2025). "Targeting MYC as a therapeutic approach offers significant potential not only to enhance treatment outcomes for this rare tumor but also to drive broader progress in the field of oncology." (PMID 40076599, 2025). "Though, MYC proteins are widely considered to be challenging to the drug for three major reasons: first, MYC proteins are not exclusively expressed in tumor cells, but are also expressed in hematopoietic cells and proliferating or regenerating healthy tissue." (PMID 40488968, 2025). "Similarly, lncRNA MYU promoted malignant growth via the miR-184/c-MYC axis, but overexpression of miR-184 downregulated c-MYC, suppressing tumour growth and metastatic potential." (PMID 41379397, 2025). "In MYC-driven tumors, where MYC amplifies RNA production, MYC-induced PRMT5 maintains efficient splicing by preventing exon skipping in transcripts like EP400, which is essential for tumor progression." (PMID 40846633, 2025). "In addition, targeting MYC can significantly increase the proportion of CD8+ T cells, thereby enhancing the killing effect of T cells on tumor cells." (PMID 40732268, 2025).
tumor (continued). "DNA methylation-based tumor classification of CNS tumors, using versions 11b6 and 12b6 of the Heidelberg classifier, as well as the NCI/Bethesda classifier indicated a consensus match to AT/RT, MYC-activated." (PMID 39833894, 2025). "Furthermore, the oe-NCL + oe-MYC + oe-TXNIP group showed a significant increase in tumor volume and ki67-positive cell ratio compared to the oe-NCL + oe-MYC + oe-NC group." (PMID 40346484, 2025). "The HepaFH3 model recapitulated many features of tumor metabolism, including glycolytic activation and dedifferentiation, yet lacked key transformation markers such as c-MYC- and BDH1-driven ketone utilization." (PMID 40862732, 2025). "The expression of oncogenic transcription factor MYC is increased in TNBC, and TNBC cells with MYC overexpression are FAO-dependent; pharmacological inhibition of FAO can significantly reduce cancer cell energy metabolism and limit tumor growth." (PMID 40256431, 2025). "miR-9 promotes GBM tumor cell proliferation and inflammation, targeting markers of the extracellular matrix and proteins involved in cell duplication and transformation, including RAS and MYC." (PMID 40141375, 2025). "Indeed, MYC upregulates mRNA expression of inhibitory immune checkpoints including CD47 and PD-L1 on tumor cells." (PMID 39706891, 2025). "MYC was upregulated in all tumor regions, but MITF activity varied—absent in P1 (dedifferentiated) and elevated in P3 and P4 (melanocytic)." (PMID 40669378, 2025). "As we uncovered an association between EIF4EBP1 and MYC mRNA expression in MB tissues, and since MYC has been described to control EIF4EBP1 transcription in other tumor types, we asked whether EIF4EBP1 also represents a MYC target gene in MBs." (PMID 40670359, 2025). "GSEA plots demonstrated significant enrichment of the “G2M checkpoint” and “MYC target pathways” in the high TEK expression group, linking TEK to cell cycle control and oncogenic transcriptional regulation, supporting its role as a tumor suppressor in RCC." (PMID 40808675, 2025). "MYC up-regulates the expression of solute carrier family 7 member 5 (SLC7A5) and solute carrier family 43 member 1 (SLC43A1), which elevates the uptake of the essential amino acids to promote tumor progression." (PMID 40290126, 2025). "Spatially, we observed co‐localization of MYC and FOSL2 in the nucleus of M‐M2 tumor cells." (PMID 39899538, 2025). "Tumour suppression occurred via direct targeting of cell division cycle 25 A (CDC25A) and c-MYC." (PMID 41379397, 2025). "By stabilizing MYC, MDM2 indirectly supports the upregulation of angiogenic factors such as VEGF, fostering the development of a robust vascular network that sustains tumor growth and facilitates invasion." (PMID 40076599, 2025). "Despite this unquestionable role of MYC in tumour development and maintenance, no MYC inhibitor has yet been approved for clinical use." (PMID 39972241, 2025). "Preclinical studies revealed that oral administration of WBC100 effectively reduced MYC protein levels in multiple tumor xenograft models, significantly inhibiting tumor growth and extending survival without overt toxicity." (PMID 40365020, 2025). "In addition, MYC regulates lactate export by stimulating the expression of monocarboxylate transporter 1/2 (MCT1/2), hence controlling lactate levels within tumor cell." (PMID 40290126, 2025). "Preclinical and clinical studies suggest that MYC-high SCLC tumors exhibit selective sensitivity to Aurora kinase A/B (AURKA/AURKB) inhibitors, such as alisertib or barasertib, which impair MYC-driven tumor growth." (PMID 40333678, 2025). "Studies using cell lines and animal models have shown that MYC overexpression alone is not sufficient to induce cell transformation or tumor development; these events require the combined activity of MYC and at least one other oncogene (e.g., RAS)." (PMID 40932956, 2025).